CRYGD (crystallin gamma D)
Description:
Crystallins are the dominant structural components of the vertebrate eye lens.
Synonyms: CRYG4; CACA; CCA3; CCP; CTRCT4; PCC; cry-g-D
Tractability: No criterion of Open Targets' tractability assessment is met for any kind of drug.
Gene: Protein-coding gene on chromosome 2 (208,121,607 to 208,124,524, reverse strand). Ensembl gene ENSG00000118231.
Subcellular location (Human Protein Atlas): Cytosol; Vesicles
Gene Ontology:
Molecular function: protein binding; structural constituent of eye lens
Biological process: cellular response to reactive oxygen species; visual perception; lens development in camera-type eye; lens fiber cell differentiation
Cellular component: cytoplasm; nucleus
Genetic constraint (gnomAD): Loss-of-function variants: 13 observed, 10.89 expected, observed/expected ratio (o/e) 1.19, 90% interval 0.77 to 1.8. The upper end of that interval is the gene's LOEUF score, 1.8, which puts it in group 6 of 6, group 1 being the genes least tolerant of losing a copy. Missense variants: 231 observed, 235.05 expected, observed/expected ratio (o/e) 0.98, 90% interval 0.88 to 1.1. Synonymous variants: 77 observed, 92.49 expected, observed/expected ratio (o/e) 0.83, 90% interval 0.69 to 1.01.
Homologues: Orthologues: chimpanzee CRYGD (100% identical), macaque CRYGD (95% identical), rabbit CRYGD (88% identical), pig CRYGD (87% identical), dog CRYGD (86% identical). Paralogues in human: CRYGB (72% identical), CRYGA (72% identical), CRYGC (71% identical), CRYGS (50% identical), CRYBB1 (35% identical), CRYBB3 (34% identical), CRYBA2 (33% identical), CRYBA4 (33% identical), CRYBB2 (33% identical), CRYBA1 (32% identical), CRYBG1 (31% identical), CRYBG3 (31% identical), and 2 more.
Diseases named in the same sentence as CRYGD in open-access papers:
CRYGD is named in the same sentence as 17 diseases in open-access papers, as found by Europe PMC text mining. Sharing a sentence is not in itself a finding about the gene and the disease. The quoted sentences say what the papers report.
congenital cataracts (9 papers, 2008 to 2024). "Approximately 59 CRYGD variants have been documented to be associated with congenital cataracts, 25 of which are unique, and the remainder are recurrent." (PMID 34840822, 2021). "γD-Crystallin (CRYGD) is a lens structural protein and its mutations are known to cause different types of congenital cataracts." (PMID 20577655, 2010). "To date, about 16 articles have reported CRYGD gene mutations that cause congenital cataracts of which about five concern coralliform cataracts." (PMID 18334953, 2008). "Mutations in the CRYGD gene may compromise the solubility and stability of crystallin proteins, thereby reducing lens transparency and leading to congenital cataracts." (PMID 38785568, 2024). "The crystallin (CRYAA, CRYAB, CRYGC, CRYGD, and CRYBA1) and connexin (GJA8, GJA3) genes were analyzed in 45 unrelated families from the Volga–Ural Region (VUR) with hereditary congenital cataracts." (PMID 37367076, 2023).
cataract (8 papers, 2009 to 2025). Partial or complete opacity of the crystalline lens of one or both eyes that decreases visual acuity and eventually results in blindness. "There is also a need to explore animal models to elucidate the underlying molecular mechanism by which CRYBB2 and CRYGD variants contribute to cataracts." (PMID 34840822, 2021). "We studied another six reported mutation sites located in the first “Greek Key” module domain of CRYGD protein as having the p.P24T mutant, such as p.R15C, p.R15S, p.P24S, p.A36P, p.R37P, and p.R37S, which have been reported to be associated with cataracts." (PMID 32148946, 2020). "Literature review shows that cataracts caused by the mutation in CRYGD had been reported in many published articles since the 1990s and that the biological function of the mutant protein was deeply and meticulously researched in many papers." (PMID 32148946, 2020). "Up to 2015, a total of 19 mutations in CRYGD were reported responsible for cataracts, most of which are missense mutations." (PMID 26147294, 2015). "Two loci, 2p24-pter and 2q33–35, have been mapped, and the specific gene, CRYGD (UniProt), in the latter locus was identified to associate with this cataract subtype." (PMID 19668596, 2009). "In this study, we investigated genetic variants in CRYAA, CRYAB, CRYGC, CRYGD, CRYBA1, GJA8, and GJA3 genes in 94 patients with congenital isolated cataracts from 45 unrelated families." (PMID 37367076, 2023). "It was proved that the C505S mutation of WFS1 contributes greatly to the occurrence of iris coloboma and corroborated that the CRYGD p.P24T possibly leads to cataract, although CRYGD p.P24T has been detected in East Asia widely and identified as having a biological function in cataracts." (PMID 32148946, 2020). "As much as 70% of autosomal dominant cataract may be accounted for by missense coding mutations in the genes for crystallins, particularly CRYAA, CRYBB2, and CRYGD, and connexins (GJA3, GJA8)." (PMID 21042563, 2010).
coralliform cataract (5 papers, 2008 to 2023). Coralliform cataract is a rare special form of congenital cataracts. "The families, clinically documented to have congenital coralliform cataracts, were screened for mutations in candidate CRYGD gene." (PMID 37480084, 2023). "Here we aimed to identify the spectrum and frequency of CRYGD gene mutations in congenital coralliform cataracts of Chinese origin." (PMID 37480084, 2023). "Previous studies had shown that mutations in the CRYGD gene can result in congenital coralliform cataracts, although an insertional mutation in the connexin 46 had also been identified causing coralliform cataract in a Chinese family." (PMID 37480084, 2023). "According to the reported pedigrees, most of the congenital coralliform cataracts resulted from CRYGD mutations." (PMID 26732753, 2016). "From the reported pedigrees, the congenital coralliform cataracts all resulted from CRYGD mutations." (PMID 21552497, 2011). "Several studies have shown that mutations in the CRYGD gene, located at 2q33–35, can result in congenital coralliform cataracts, and the P24T mutation of CRYGD has been reported in multiple cases." (PMID 21552497, 2011). "By directly sequencing the coding region of CRYGD, we identified a recurrent (p.P24T) mutation in two unrelated families with congenital coralliform cataracts and three novel (p.Q101X, p.E104fsX4 and p.E135X) mutations in three families with congenital nuclear cataracts." (PMID 26732753, 2016). "Allelic heterogeneity also accounts for the two different cataract phenotypes, nuclear and coralliform cataracts, that may be caused by mutations in the CRYGD gene." (PMID 23288985, 2012). "Therefore, it is appropriate to consider the CRYGD gene as the top list of functional candidates in congenital coralliform cataracts." (PMID 37480084, 2023). "Although previous studies had shown that mutations in the γD-crystallin (CRYGD) can result in congenital coralliform cataracts, no conclusive genotype-phenotype correlation might be drawn." (PMID 37480084, 2023). "We identified a recurrent p.P24T mutation in 10 of 12 unrelated families, accounting for 83.3% of coralliform cataracts, and no other mutations in CRYGD were detected, which indicated that CRYGD might play an important role in the development of congenital coralliform cataract." (PMID 37480084, 2023).
autosomal dominant cataract (2 papers, 2010 to 2011). A syndromic cataract that has autosomal dominant inheritance. "Mutations in the γ-crystallin gene (most commonly CRYGC and CRYGD) are responsible for multiple types of autosomal dominant cataracts, including pulverulent, aceuliform, cerulean, and lamellar cataracts." (PMID 22219628, 2011). "Mutations in CRYGC and CRYGD have been identified to cause autosomal dominant congenital cataract as a result of altered stability, association and/or solubility of γ-crystallins." (PMID 22219628, 2011).
cervical cancer (1 paper, 2023). A primary or metastatic malignant neoplasm involving the cervix. "The enriched genes included CD4 in cervical cancer, VPS52, NUP62, CRYGD, IL34, GATA3 in prostate cancer and F11, TXNIP, KIT, ASGR2, SERPINF1 in liver cancer, which also provide insight into the molecular mechanisms underlying cancer progression and the potential impact on patient survival." (PMID 37393582, 2023).
Coats disease (1 paper, 2016). Coats disease (CD) is an idiopathic disorder characterized by retinal telangiectasia with deposition of intraretinal or subretinal exudates, potentially leading to retinal detachment and unilateral blindness. "Of the identified DCPs, several crystalline-related proteins, including CRYBB1, CRYBB2, CRYGS and CRYGD, were down-regulated in the AH from patients with Coats' disease." (PMID 27416065, 2016).
COVID-19 (1 paper, 2023). A disease caused by infection with severe acute respiratory syndrome coronavirus 2. "Endocrine-specific genes (e.g., HSD3B2, INS, IAPP, TSHR, FOXE1, LEP, and CRYGD) were deregulated in COVID-19 cases in an organ-specific manner." (PMID 37246981, 2023). "Hence, the downregulation of CRYGD may be consistent with alterations of the menstrual cycle observed in women recovering from COVID-19." (PMID 37246981, 2023).
iris coloboma (1 paper, 2020). "This is the first time the association of WFS1 p.C505S with iris coloboma has been demonstrated, although CRYGD p.P24T has been widely reported as being associated with congenital cataract, especially in the Eastern Asian population." (PMID 32148946, 2020). "We report a novel mutation, WFS1 p.C505S, and a known mutation, CRYGD p.P24T, that cosegregate with iris coloboma and congenital cataract, respectively, in a Chinese family." (PMID 32148946, 2020). "In addition, some research indicated that the mutation of WFS1 may also cause cataract, so we cannot exclude the possibility that the joint action of the CRYGD and WFS1 cause cataract and iris coloboma." (PMID 32148946, 2020).
X-linked recessive disease (1 paper, 2024). X-linked recessive form of disease. "In detail, five autosomal dominant (AD) ophthalmic diseases caused by variants in ABCA4, CRYGD, MYOC, RPL1L1, and TGFBI, one AR disease caused by the PDE6B variant, and one X-linked recessive disease caused by the OCRL variant were determined as genetic causes." (PMID 38785568, 2024).
cancer (2 papers, 2022 to 2023). A tumor composed of atypical neoplastic, often pleomorphic cells that invade other tissues. "Genes such FAM182A, SOX9, AHNAK2, ENSG00000121031, FLT3LG, PMEPA1, ZFP36L2 in the large intestine, ALB, KRTAP19-1, APOB, CD200, CRYGD, KRTAP24-1, OR6N2 in the liver are novel predictions, and their functions in these cancers can further be studied." (PMID 34997044, 2022).
CRYGD also shares sentences with these, for which no sentence is quoted: nuclear cataract (4 papers); Anterior polar cataract (1); bladder cancer (1); infection (1); liver cancer (1); Nystagmus (1); prostate carcinoma (1).